ZEB1 (zinc finger E-box binding homeobox 1)
Diseases named in the same sentence as ZEB1 in open-access papers (continued):
Sharing a sentence is not in itself a finding about the gene and the disease.
ovarian carcinoma (continued). "However, restoration of the miR-200c served as a tumor suppressor by directly targeting the zinc-finger E-box binding homeobox 1 (ZEB1) to inhibit EMT and ovarian cancer metastasis." (PMID 23842108, 2013). "In addition, our studies suggest that FGF2 exerts its effects in human ovarian cancer cells via the activation of the PI3K/Akt/mTOR and MAPK/ERK signaling pathways and the subsequent increased expression of Slug and ZEB1." (PMID 23554977, 2013). "Our study in ovarian cancer epithelial cells consistently showed that MECOM loss, as well as JIB-04 treatment, downregulated ZEB1 along with its non-canonical targets, N-cadherin and vimentin, suggesting potential transcriptional regulation of N-cadherin and vimentin." (PMID 40664642, 2025). "ZEB1 expression may occur concurrently with chemoresistance in ovarian cancer but is not a marker of the platinum/taxane cross resistance phenotype." (PMID 35794446, 2022). "ZEB1 is predictive of overall survival in ovarian cancer, but not in platinum-treated patients." (PMID 35794446, 2022). "ZEB1 is predictive of overall survival but not in ovarian-cancer patients treated with platinum." (PMID 35794446, 2022). "Similarly, ChIP-seq experiments showed no binding of GRHL2 to the Zeb1 or Zeb2 promoters in kidney, placenta, ovarian cancer or lung epithelial cells." (PMID 32005677, 2020). "Therefore, the tight repression of E-cadherin in full mesenchymal ovarian carcinoma cells such as HEYA8, which may involve ZEB1-independent nucleosome assembly or chromatin rearrangements that hinder GRHL2 binding, remains to be elucidated." (PMID 31372511, 2019). "Furthermore, our in vitro data suggested that CD44 may promote ovarian cancer progression through the EMT process by regulating Snail and ZEB1." (PMID 31497537, 2019). "We conclude that ectopic ZEB1 expression is sufficient to upregulate NNMT and other mesenchymal genes, enable cells to use methylated substrates as an alternative energy sources, and induce glucose independence in glucose-dependent epithelial ovarian cancer cell lines." (PMID 28412735, 2017). "Higher expression of ZEB1 and ZEB2 were found in diverse types of cancer including ovarian carcinoma, suggesting that the two factors may play an essential role in EMT of ovarian carcinoma." (PMID 24677166, 2014). "Furthermore, we show that restoration of miR-200c in Hey ovarian cancer cells results in a dramatic decrease in migration and invasion even though E-cadherin is not restored in these cells, despite complete repression of ZEB1." (PMID 20049172, 2010). "Furthermore, a recent study demonstrated that EMT is required for EGF-induced large gastric cancer (LGC) and ovarian cancer cell migration and invasion, and that EGF-induced EMT involves activation of the ERK1/2 and PI3K/AKT pathways with subsequent induction of Snail, Slug, and ZEB1 expression." (PMID 24945379, 2014). "We validated these results by overexpressing ZEB1 in another ovarian cancer cell line of serous histology (OVCA433), which shows no detectable endogenous expression of NNMT or ZEB1." (PMID 28412735, 2017). "Additionally, ZEB1 was not induced by estrogen treatment in OVCAR3 and Caov-3 ovarian cancer cell lines, but it was promptly induced after one hour in a different ovarian cancer cell line, OV266." (PMID 26797644, 2016). "Many of the other EMT-related transcription factors, such as SNAI2, TWIST1, and ZEB1 are often overexpressed in the MAF signature, but SNAI1 is not (and, at least in ovarian carcinoma in which we have methylation data, this is due to its differentially methylated status)." (PMID 21047417, 2010).
melanoma (141 papers, 2013 to 2025). A malignant, usually aggressive tumor composed of atypical, neoplastic melanocytes. "In clinical research, reduced ZEB2 levels correlated with lower survival rates in melanoma patients, whereas elevated ZEB1 expression was linked to poorer clinical prognoses." (PMID 40356596, 2025). "Loss of KPC1 in melanoma cells prevented ZEB1 proteasomal-mediated degradation, increased expression of mesenchymal markers, and enhanced MM cells migration." (PMID 41429767, 2025). "In human melanoma samples, high ZEB1 levels were found to be associated with decreased CD8+ T cell infiltration." (PMID 38426087, 2024). "We also found a positive correlation in three out of five ZEB1int melanomas, where ZEB1-positive areas were tightly associated with high corresponding Tspan8 expression areas." (PMID 38398085, 2024). "For instance, high expression of ZEB1 is associated with a reduction in CD8+ T cell infiltration in human melanoma samples." (PMID 38835341, 2024). "We define ZEB1 as a major transcriptional regulator of genes associated with phenotypic transitions in melanoma." (PMID 38519642, 2024). "In melanoma, it has been shown that ZEB1-mediated phenotype switching is associated with drug resistance (MAPK inhibitors), as well as for positive Oct4 cells exhibiting stem cell-like features." (PMID 37189846, 2023). "Gain- or loss-of-function experiments in BRAF or NRAS-mutated melanoma mouse models demonstrated that ZEB1 prevents the recruitment and the activation of CD8+ T cells." (PMID 35432344, 2022). "Multi-immunofluorescence spatial analyses of the immune infiltrates in human melanoma samples highlighted that high ZEB1 expression in tumor cells was associated with decreased CD8+ T lymphocyte infiltration." (PMID 35432344, 2022). "In clinical studies, ZEB2 deficiency was associated with reduced survival in melanoma patients, while ZEB1 expression was associated with poorer clinical outcomes." (PMID 36076302, 2022). "It showed that the mutation of ZEB1 would lead to shorter OS in patients with melanoma (P < 0.001), while the progression survival time (PFS) of patients with the mutation of CP was significantly decreased (P < 0.05)." (PMID 35232428, 2022). "It was reported that ZEB1 expression is associated with an invasive phenotype while ZEB2 expression is required for the proliferative melanoma cell state." (PMID 36232952, 2022). "In melanoma, ZEB1 and ZEB2 seem to be associated with antagonistic effects on TGF-β signalling, as is described in the following sections." (PMID 32796736, 2020). "A progressive loss of ZEB2/SNAIL2 and a gain in TWIST1/ZEB1 expression were observed along the transition from melanocytes to malignant melanoma." (PMID 32759677, 2020). "Accordingly, the switch from ZEB2 to ZEB1 in the NRAS melanoma mouse model is associated with the gain of an invasive phenotype." (PMID 32759677, 2020). "Gain- or loss-of-function experiments of ZEB1 in human melanoma cells demonstrated that ZEB1 regulates reversible switching between the proliferative and the invasive phenotype." (PMID 32759677, 2020). "Fisetin and sorafenib reduced the expression of Snail1, Twist1, Slug and ZEB1 in BRAF-mutated melanoma cells." (PMID 26517521, 2016). "Analyses of larger patient cohorts are required to validate the use of ZEB1 as a predictive marker in order to stratify BRAF‐mutated melanoma into MAPKi‐sensitive and MAPKi‐resistant subgroups." (PMID 27596438, 2016). "Indeed, the loss of SNAI2/ZEB2 combined with the gain of ZEB1 is a factor involved in the poor prognosis of melanoma patients and is associated with resistance to MAPK-targeting and immune therapies." (PMID 38398085, 2024). "ZEB1 has also been associated with M2 macrophage polarization and PD-L1 expression increases in lung adenocarcinoma, however, these factors remain to be explored in melanoma." (PMID 38426087, 2024).
melanoma (continued). "Indeed, we previously showed that ZEB1 expression in melanoma cells was associated with decreased CD8+ T cell infiltration in melanoma tumors." (PMID 38398085, 2024). "The expression pattern of EMT-transcription factors, such as Slug and ZEB1, revealed an opposite trend, which is typical of melanoma cells; they could mediate a phenotype switch associated with resistance to the BRAF inhibitor." (PMID 37189846, 2023). "In addition to promoting CD8+ T cell deficiency, ZEB1 overexpression in melanoma mouse models was also associated with an increased frequency of Treg, although at a later stage." (PMID 35432344, 2022). "It showed that the mutation of ZEB1 could cause a significant decrease in the OS in melanoma patients, and mutation of CP was closely related to the progression of the tumor." (PMID 35232428, 2022). "The epigenetic regulator EZH2, was recently shown to coordinate melanoma cell dedifferentiation (associated with a gain in ZEB1 and NGFR) with downregulation of MHC class I (HLA-A/B/C) and antigen presentation machinery (i.e. antigen processing genes TAP1/2 and immunoproteasome subunits PSMB8/9)." (PMID 35432344, 2022). "This indicated that the mutation of ZEB1 may influence OS of melanoma patients and mutation of CP may be related to tumor progression." (PMID 35232428, 2022). "We also investigated the correlation of the seven prognostic-associated TBCs between MMP-related genes (MMP2, MMP9, MMP7, MMP14, BSG, EGFR, MMP1, MMP3) and EMT-associated genes (TWIST1, VIM, CDH2, ACTA2, ZEB1), which also indicated a central role of TBCs in melanoma." (PMID 33194704, 2020). "Strong ZEB1 expression is also associated with increased therapy resistance in melanoma cells." (PMID 32796736, 2020). "We herein wondered whether high ZEB1/TWIST1 expression may be associated with the resistance to MAPKi in melanoma, with the final aim of testing whether targeting these factors in combination with MAPKi could prevent the emergence of resistance." (PMID 27596438, 2016). "To assess whether there is an association between the levels of HMGA2, Twist1 or ZEB1 and miR-33b in melanoma, we analyzed their levels in 72 melanoma patient samples." (PMID 25868853, 2015). "Since the malignant melanocytes can spread to distant locations and cause metastasis this process is involved in the EMT of melanoma in which miR200c and ZEB1 may be downregulation or upregulation." (PMID 24625224, 2014). "In melanoma, ZEB1-driven phenotype switching mimics neural crest-like plasticity, while SOX10 re-expression drives dedifferentiation and therapy resistance." (PMID 41462674, 2025). "ZEB1, an epithelial-mesenchymal transition (EMT)-inducing transcription factor, has recently been discovered to be expressed in melanoma cells in association with a decrease in CD8+ T-cell infiltration independent of β-catenin pathway activation." (PMID 40097979, 2025). "ZEB1 is a major regulatorof melanoma cell plasticity, driving resistance to mitogen-activatedprotein kinase-targeted therapies." (PMID 40621031, 2025). "NFKB, CDH1, and ZEB1 are therefore potential master regulators for genes differentially expressed in melanoma microsatellites." (PMID 40717170, 2025). "Expression of the ZEB1 transcription factor is frequently activated in melanoma, where it fosters adaptive resistance to targeted therapies." (PMID 38519642, 2024). "In order to study the role of endogenous ZEB1 during phenotypic transitions in melanoma cells, we used two BRAFV600 patient-derived short-term cultures, established with a low number of passages after culture (GLO and C-09.10)." (PMID 38519642, 2024). "Nonetheless, cell type-specific targets are particularly expected, given the antagonistic functions of ZEB1/ZEB2 in melanoma." (PMID 38519642, 2024). "To further investigate the correlation between the expression of ZEB1 and markers of melanoma cell states at the single-cell level, we first used publicly available single-cell RNA-seq datasets." (PMID 38519642, 2024).
melanoma (continued). "Altogether, we were able to create and validate the melanoma-specific ZEB1 regulon and confirm the activity of ZEB1 in mesenchymal and neural-crest-like cells in melanoma at single cell level." (PMID 38519642, 2024). "Overall, this study defines ZEB1 as a major regulator of melanoma cell identity and phenotype switching." (PMID 38519642, 2024). "Evidence shows the ZEB2 to ZEB1 switch drives invasion and furthers the dedifferentiation of melanoma cells." (PMID 38426087, 2024). "Among the miRNAs that potentially modulate ZEB1 in the proposed network, we can highlight some that have been reported in the literature to act on other molecular targets in melanoma." (PMID 39594467, 2024). "Intra-tumor heterogeneity of markers of melanoma cell states according to ZEB1 expression in human samples demonstrated co-expression of ZEB1 with both stem-like and invasive markers, highlighting the relevance of ZEB1 in these two sub-populations." (PMID 38519642, 2024). "We also found that ZEB1’s effect on the biomechanical properties of melanoma cells was dependent on Tspan8’s function, since the significant stiffness decrease induced by ZEB1 overexpression was abolished upon Tspan8 knockdown." (PMID 38398085, 2024). "We validated the increased activity of the ZEB1-melanoma-specific regulon in single-cell-RNA-seq data in both Neural-Crest-like and Mesenchymal populations." (PMID 38519642, 2024). "Here, we performed a genome-wide characterization of ZEB1 transcriptional targets, by combining ChIP-sequencing and RNA-sequencing, upon phenotype switching in melanoma models." (PMID 38519642, 2024). "Our study reports a genome-wide characterization of the transcriptional functions of ZEB1 in melanoma, providing a better understanding of the molecular mechanisms underlying phenotype plasticity and intra-tumor heterogeneity in melanoma." (PMID 38519642, 2024). "We observed that Zeb1’s stable overexpression in melanoma cells, known to induce invasive signatures, was sufficient to significantly decrease cell stiffness." (PMID 38398085, 2024). "p3 anoikis-resistant melanoma cells showed a higher level of the EMT markers N-Cadherin, Vimentin, Zeb1, and SNAIL1, associated with high invasive ability and low IKB expression, which indicates NF-kB activation." (PMID 39175551, 2024). "ZEB2 is expressed in normal melanocytes and its expression progressively decreases during transformation to melanoma, while ZEB1 expression increases." (PMID 38519642, 2024). "We demonstrated that ZEB1 overexpression in melanoma cells was indeed able to activate Tspan8 mRNA and protein expression." (PMID 38398085, 2024). "We identified and validated the direct binding of the ZEB1 transcription factor to the promoter of genes specific to the melanocytic lineage or driving melanoma cell identity." (PMID 38519642, 2024). "We previously showed that a switch from ZEB2 to ZEB1 expression is a poor prognostic factor in melanoma." (PMID 38519642, 2024). "We observed a significant decrease in SNAI2 mRNA expression correlated with an increase in ZEB1 mRNA and protein expression along with melanoma progression towards an invasive state." (PMID 38398085, 2024). "We collected samples from mitf::Xmrk/+ medaka and compared SNAI2, ZEB1, and Tspan8 expression in normal skin, primary melanomas, and melanoma local metastases." (PMID 38398085, 2024). "A recent report utilizing a melanoma mouse model found ZEB1 expression decreases immunostimulant T-cell chemokines and impairs CD8+ T cell recruitment." (PMID 38426087, 2024). "Zeb1 and Zeb2, both mesenchymal markers in the epithelial context, are inversely related in melanoma." (PMID 38247872, 2024). "Given the lack of relevance of the ZEB1 regulon from the DoRothEA database in the context of melanoma, we processed our data to define a melanoma specific ZEB1 regulon (referred to as ZEB1.mel), that would be a useful tool for the scientific community." (PMID 38519642, 2024).
melanoma (continued). "Quantitative analyses of SOX10 intensity according to ZEB1 expression level (high, intermediate, low and negative) confirmed a significant decrease in SOX10 levels when ZEB1 expression increases in melanoma cells." (PMID 38519642, 2024). "Overall, our results show that the modulation of EMT-TF expression, resulting in ZEB1 overexpression, which is crucial for melanoma progression, is sufficient to remodel the melanoma cell shape and alter their biomechanical properties." (PMID 38398085, 2024). "We further designed a melanoma-specific ZEB1 regulon which can be used by the scientific community to accurately study ZEB1 transcription factor activity in a melanoma context." (PMID 38519642, 2024). "These transcription factors, and ZEB1 especially, have been previously shown by our laboratory as playing a central role in melanoma cell plasticity acquisition and driving both outcomes and therapy resistance in cutaneous melanoma patients." (PMID 38398085, 2024). "In particular, a decrease in ZEB2/SNAIL2 levels and a rise in TWIST1/ZEB1 levels have been shown during the transition from melanocytes to malignant melanoma." (PMID 37189846, 2023). "High levels of ZEB1/Slug and Oct4 expression, as we showed here, certainly sustain an invasive phenotype in melanoma, including increased expression of vimentin." (PMID 37189846, 2023). "Along similar lines, ZEB1 has been shown to participate in the initialization and progression of melanoma cells." (PMID 37601651, 2023). "The downregulation of Slug and Zeb2, and upregulation of Zeb1, Snail and Twist1 promote differentiation and metastasis in melanoma cells." (PMID 37181747, 2023). "ZEB1 expression promotes immune escape in melanoma and is involved in the acquisition of resistance to MAPK inhibitors." (PMID 37511550, 2023). "Several studies have reported that increased expression of Zeb1 in melanoma is involved in phenotype change into an invasive one." (PMID 36776217, 2023). "In contrast, ALOX5, CISD1, ATP5MC3, NFS1, EMC2, ZEB1 are highly expressed in normal tissues, and they are related to the good prognosis of melanoma patients." (PMID 36313708, 2022). "Our analysis showed that EMT markers like N‐cadherin, ZEB1, ADAMTS9 and ITGA8, which were shown to regulate invasion in melanoma, where associated with low NRF2 target gene expression." (PMID 34951143, 2022). "To further investigate the relationship between nPKC-θ and dysfunctional T-cell transcription, we assessed interactions between PKC-θ and ZEB1 in PD-1+/CD8+ T cells isolated from immunotherapy-responsive or -resistant melanoma patients." (PMID 35326747, 2022). "In parallel, we already demonstrated the power of multiplexed immunofluorescence analyses to specifically analyze ZEB1 expression in melanoma cells, by excluding stromal and immune cells." (PMID 35432344, 2022). "In parallel experiments, the silencing of NF-κB drives a rapid increase of ERβ and a decrease of EMT markers, N-cadherin, vimentin, Zeb1, both in female and male melanoma cells." (PMID 36499700, 2022). "After silencing ERβ both in female and male melanoma cells, we found, in addition to an increase of Zeb1, also a significant reduction of IkB, which leads to NF-κB activation." (PMID 36499700, 2022). "For instance, ZEB1 was shown to promote the progression of melanoma, whereas ZEB2 functions as a tumor suppressor to inhibit this process." (PMID 35601657, 2022). "Low expression of ZEB1 in melanoma patients was closely related to short OS and DFS (OS: P = 6e−06; DFS: P = 0.0053)." (PMID 35232428, 2022). "Evidence from in vivo models and human clinical samples has led to a proposed model of phenotype switching during melanoma progression, fine-tuned by ZEB1/2, TWIST1, and SNAIL2, as well as MITF expression." (PMID 35267510, 2022). "More importantly, we find that CP and ZEB1 have special effects in melanoma, which also provides a new insight for future research exploring molecular mechanism and drug treatment in melanoma." (PMID 35232428, 2022).